CXCL13 (C-X-C motif chemokine ligand 13)
Diseases named in the same sentence as CXCL13 in open-access papers (continued):
Sharing a sentence is not in itself a finding about the gene and the disease.
cancer (continued). "The significant KEGG pathways are chemokine signaling pathway (CCL5, CCL18, CCL19, CCL21, CXCL12, CXCL14, CXCL13), ​​NF-kappa B signaling pathway (CCL19, CCL21, CXCL12), intestinal immune network for IgA production (TNFRSF17, CXCL12), pathways in cancer (IGF1, CXCL12)." (PMID 35486660, 2022). "These CTLs secreted CXCL13 to recruit more CXCR5+ immune cells and to lyse CXCR5+ cancer cells." (PMID 35392977, 2022). "A similar CXCL13+ CD103 (ITGAE)+ CD8+ T cell subtype was previously suggested to play potential roles in mediating B cell recruitment and tertiary lymphoid structure formation in human cancer." (PMID 36423636, 2022). "In summary, the CXCL13/CXCR5 signaling in T cells, B cells, and cancer cells are similar." (PMID 35053457, 2022). "An increasing number of studies have identified that various influences of CXCL13 expression levels prognosis in patients with cancer regardless of immunotherapy treatments." (PMID 35053457, 2022). "However, recent gene knockdown/suppression findings including the neutralization of overexpressed CXCL13 and/or CXCR5 activities have shown the therapeutic potential/validation of this pathway in many kinds of human cancers [22, 33−35]." (PMID 34922542, 2021). "Based on these findings, we hypothesized that T cells expressing an EGFR-targeting CAR and the CXCR5 receptor will pair with CXCL13 produced by NSCLC tumors, further enhancing the T cell migration and cancer cell killing." (PMID 34553036, 2021). "It suggests that SAA1, CXCL10, CCR5, CCL19, CXCL11, CXCL13, and CCL5 have important function in immunotherapy for cancer patients, and may be used as key regulator genes of immunotherapy." (PMID 34093667, 2021). "In addition, CXCL13/CXCR5 axis activates the phosphatidylinositol‐3 kinase (PI3K)/AKT pathway, leading to invasion and migration of cancer cells." (PMID 32314548, 2020). "Cancer CD4, CXCL13, and FOXP3 expression correlated positively with each other (P ≤ 0.001)." (PMID 29482642, 2018). "Using transwell migration analysis, we observed that MDSC from WT and KO mice had comparable migration capacities under baseline conditions (no cancer cells or exogenous CXCL13)." (PMID 26462153, 2015). "Future studies are needed to examine this issue, as it appears that no previous studies on murine CXCL13 expression in NOD-SCID models of cancer appear to have been reported." (PMID 23936541, 2013). "It was identified that HAVCR2 had positive infiltration scores in all cancer types, whereas a negative infiltration score was noted for CXCL13 (in LGG and DLBCL), LAG3 (in DLBCL and AML), LAYN (in CHOL, KICH, AML, LGG, PCPG, THCA and UCS), PDCD1 (in DLBCL, AML and THYM) and TIGIT (DLBCL and AML)." (PMID 40076932, 2025). "This suggests that serum CXCL13 protein may not necessarily be secreted due to chronic inflammation in cancer tissues." (PMID 39344390, 2024). "However, it is important to recognize that CXCL13 does not act in isolation but rather interacts with multiple signals from cancer cells and surrounding cells, contributing to cancer development." (PMID 39344390, 2024). "For example, cancer-associated fibroblasts (CAFs), which are prominent in non-small cell lung cancer, can significantly increase CD4+ and CD8+ T cells through TGF-β, inducing the production of CXCL13 and promoting TLS formation." (PMID 39840050, 2024). "Furthermore, the expression of CXCL 13 was positively correlated with CD8+ T cell percentage in most cancers, while the correlation between CXCL13 expression with CD4+ T cell and NK cell was not identified." (PMID 37540227, 2023). "The pro-cancer and anti-cancer effects of CXCL13-CXCR5 axis on NSCLC still remain to be studied, and some scholars have pointed out that it is a poor prognostic factor for immunotherapy because of the presence of PD-1 on the surface of CXCL13+ T cells and CXCR5+ T cells." (PMID 38124739, 2023). "However, no comprehensive reviews of the role of CXCL13 in cancer immunotherapy have been published to date." (PMID 35053457, 2022).
cancer (continued). "This review aims to provide an overview of the CXCL13/CXCR5 signaling axis to summarize its mechanisms of action in cancer cells and lymphocytes, in addition to effects on immunity and cancer pathobiology, and its potential as a biomarker for the response to cancer immunotherapy." (PMID 35053457, 2022). "In response to combination therapy, CXCL13 produced by ASPH+ expressing HCC or TNBC cell was capable of recruiting immune cells, especially CXCR5+/CD8+ TILs (including a proportion of CTLs), to participate in forming TLSs and to execute cytotoxicity against cancer cells." (PMID 35392977, 2022). "Thus, complex network involving tumoral and stromal (immune) CXCL13 and CXCR5 integrate to promote cancer cell autonomous and non-autonomous responses, highlighting autocrine, paracrine and endocrine interactions in dictating aggressive cancer phenotypes." (PMID 35392977, 2022). "The CXCL13/CXCR5 axis makes pivotal contributions to the initiation and progression of tumors, and therefore may serve as an attractive therapeutic target for related malignant neoplasms." (PMID 34947813, 2021). "Moreover, upregulation of CXCL13 and CXCL14 are associated with a reduction in HLA-DRA and MHC-Class II, because of which cancer-specific antigens are not presented by dendritic cells and hence cancer cells evade immunosurveillance." (PMID 32752229, 2020). "However, when the genes for CXCL13 or its binding partner were deleted, the mice no longer got cancer when exposed to the PAH." (PMID 26565418, 2015). "The possibility also exists that overexpression of murine CXCL13 may be a common phenomenon in many NOD-SCID models of cancer, B cell-related or not." (PMID 23936541, 2013). "Our research in the three cohorts confirmed that the presence of CXCL13+ T cells is a strong determinant of ICB response and could be served as potential targets for improving ICB response, not only in the first reported CRC multiomics dataset but also in a broader pan-cancer context." (PMID 40054456, 2025). "Therefore, we could not assess the significance of CXCL13 derived from CD4+ T cells on the formation of TLS in our mouse cancer models." (PMID 35552285, 2022). "We first confirmed CXCL13 expression in NSCLC patient blood and cancer tissues and the absence of CXCR5 expression in normal CD3 T cells." (PMID 34553036, 2021). "Surprisingly, despite a clear activation of the non-canonical NF-κB pathway in the cancer cells tested, they did not secrete the chemokines CXCL12, CXCL13, CCL19 and CCL21, known to be induced as a consequence of activation of this signaling pathway upon LTβR stimulation of other cell types." (PMID 39215104, 2024). "Then, a pan-cancer differential expression analysis was performed, and we found that genes such as CXCL13, ITM2A, NR3C1, SRGN, COTL1, and PDCD1 were significantly up-regulated in SC-2 cells compared with other cells in at least five cancer types, but not in SC-10 cells." (PMID 36049666, 2023). "CXCL13-producing non-cancerous cells in the TME, such as myofibroblasts, myeloid cells, B cells, and T cells, may also serve as potential targets for cancer therapy." (PMID 34947813, 2021). "Retaining cytotoxicity while increasing production of chemokines such as CXCL13, to increase TLS formation and strengthen humoral as well as cell mediated immunity, could prevent dissemination of an infectious agent, or cancer, which can be contained but not eliminated." (PMID 37520560, 2023). "Thus, the complex networks of cellular interactions involving tumoral CXCL13 and CXCR5 integrate to promote cancer cell autonomous and non-autonomous responses, highlighting the relevance of autocrine and paracrine interactions in dictating the cancer phenotype." (PMID 31354634, 2019).
cancer (continued). "We found that BaP or CXCL13 treatment or SPP1 overexpression in lung epithelial or cancer cells did not up-regulate RANKL or Src (data not shown), but did activate β–catenin, suggesting that CXCL13 may induce an EMT via different mechanisms in different settings." (PMID 26565418, 2015).
infection (126 papers, 2008 to 2025). The state of being infected such as from the introduction of a foreign agent such as serum, vaccine, antigenic substance or organism. "CXCL13 increases in response to infection and is classically associated with germinal center formation during adaptive immune responses." (PMID 37917623, 2023). "In contrast, at day 21 after infection, most CXCL13 is associated with MadCAM-1+ cells, which are distributed throughout the WP and are not restricted to the marginal sinus." (PMID 36950118, 2023). "Transcripts encoding the chemokines CCL2, CCL3 (MIP-1α), IL8, and CXCL13 showed the greatest abundance 24 h after infection with either Makona or RESTV." (PMID 31689981, 2019). "In summary, although CXCL13 is higher in complicated CNS inflammation and, therefore, might be a marker of the severity of the infection; the diagnostic accuracy is insufficient to distinguish between complicated and uncomplicated disease courses." (PMID 38203597, 2023). "In bacterial and viral neuroinfections, we have little data compared to LNB and are constrained to assumptions about the underlying immune process, for example that CXCL13 elevations signal progressing infections necessitating a prolonged or intensified immune help from peripheral blood." (PMID 30660201, 2019). "Hence, high levels of CXCL13 early in infection were associated with emergence of cross-neutralizing antibodies within 1 year PI." (PMID 28943879, 2017). "Hence our data from subtype C hyperacute infection confirm the utility of CXCL13 levels early in infection as a biomarker for possible superior GC activity associated with emergence of cross-neutralization antibodies." (PMID 28943879, 2017). "Importantly, daily treatment with aprepitant significantly attenuated infection-associated increases in CXCL13 and CCL2 mRNA expression." (PMID 28202084, 2017). "Our findings revealed that CXCL13 expression was significantly increased after infection for 24 hours in THP-1 cells." (PMID 40264781, 2025). "No significant changes in any of the mediators measured were induced by infection, except for CXCL13, which increased in the infected animals at 28 DPI." (PMID 40576342, 2025). "CCL21 protein and mRNA remained low at day 3 post-infection, and Cxcl12 and Cxcl13 were also repressed." (PMID 39708807, 2025). "Levels of CXCL13, a B cell chemoattractant, increased following infection but reached a nadir after treatment." (PMID 40576342, 2025). "The ligand for CXCR5, namely, CXCL13, is inducible in the murine lung following infection with Mtb (28, –, 30)." (PMID 38407132, 2024). "Accordingly, we observed a modest increase in M-type specific serum IgG after 2x infections, coinciding with the initial increase in CXCL13 systemic levels." (PMID 38576622, 2024). "We assessed the level of CXCL13 in mouse sera collected three days and three weeks after each homologous sequential IN infection." (PMID 38576622, 2024). "The gene expression of the chemokines involved in T cell and B cell recruitment, Ccl21 and Cxcl13 were both significantly increased in the salivary glands during LucAdV5 infection compared to uninfected tissue." (PMID 39355243, 2024). "B cells found in granulomas produce the chemokine CXCL13, which recruits specific T cells to the infection site, promoting follicle-like structure formation within granulomas." (PMID 39717773, 2024). "Although CXCL13 demonstrated a transient, albeit significant, increase following each IN infection, serum IgG titers remained consistent." (PMID 38576622, 2024). "Key amongst these chemokines are CCL21 and CXCL13, which are required for normal T zone and follicle segregation and 24 h after STm infection changes in expression of these chemokines have been reported." (PMID 36950118, 2023). "In the preliminary experiment, the levels of CXCL13 mRNA expression in FMDV-infected BMDMs were significantly increased as early as 24 h after infection." (PMID 37047294, 2023).
infection (continued). "Some up-regulated genes at 21 dpi (e.g., Ltf, Cxcl9, Pglyrp1, Prg2, Cxcl13, Cxcl3, Ccl9, Ccl19, Krt5, Krt14, Krt15, Krt17, and Slpi) were also identified in a previous infection study by using H1N1(PR8)." (PMID 38005876, 2023). "Recently, it has been shown that CXCL13 levels in plasma provides strong indication for germinal centers activities in response to vaccines and infections." (PMID 35061851, 2022). "We propose that in SJL mice, TMEV‐infection drives an early and excessive CXCL13 production in various cell types, which promotes accumulation and survival of B cells in the CNS." (PMID 34231271, 2021). "The time course RT-qPCR analysis demonstrated a dramatic increase in the expression of the proinflammatory cytokine mRNAs for CXCL-13, IFNγ, and IL-6 with infection." (PMID 34451461, 2021). "In a longitudinal study conducted in Canada, HIV-1-infected individuals sampled during both acute and chronic phases of infection showed higher plasma levels of CXCL13 compared to elite controllers and healthy controls." (PMID 33732259, 2021). "The authors demonstrated that among patients with a complicated infection course (bacterial and viral), 50% at admission and 100% at follow-up had markedly elevated CXCL13 levels." (PMID 34638953, 2021). "In the present study, mRNA and protein levels of CXCL13 were upregulated very early in the infection course, and the levels were significantly higher in TMEV‐infected SJL when compared with TMEV‐infected B6 mice." (PMID 34231271, 2021). "; however a large proportion of CXCL13 was expressed by lung leukocytes during the late infection stage (8 d.p.i)." (PMID 34868067, 2021). "Infection of the CNS induces production of CXCL13 in microglia, macrophages, and endothelial cells there." (PMID 34711216, 2021). "We also observed that the chemokine CXCL13 was particularly elevated in patients who succumbed to infection." (PMID 33472985, 2021). "We further found that CXCL13 was expressed mainly by lung tissue cells during the early infection stage (3 d.p.i)." (PMID 34868067, 2021). "C-X-C motif chemokine 13 (CXCL13) helps mediate the inflammatory response to infection and injury, and it exerts local, concentration-dependent effects on hippocampal memory function." (PMID 33161894, 2020). "H. felis infection up-regulated Cxcl13 expression in WT mice after 25 weeks of infection, while its expression was barely induced in MyD88−/− infected mice." (PMID 31065023, 2019). "We next investigated the occurrence of CXCL13 elevations in patients dichotomized by type of infection to avoid bacterial or viral etiology biasing results." (PMID 30660201, 2019). "Further, inoculation with LPS or whole Pseudomonas aeruginosa bacteria results in ectopic lung GC structures that lack FDC, in contrast to the CXCL13-expressing FDC observed following infection with modified vaccinia virus Ankara." (PMID 30984186, 2019). "The role of host immunological factors is less clear but includes the maintenance of a high level of T follicular helper cells, increased levels of CXCL13 early in infection, autoimmunity and ethnicity." (PMID 29630668, 2018). "Similar to others, we found that levels of CXCL13 were higher in bNAb individuals early in infection suggesting that this cytokine provides important signals for bNAb development." (PMID 29630668, 2018). "FDCs are responsible for coordinating these events but have a decreased area in LN of aged mice compared to their adult counterparts, and less CXCL13 protein is produced in response to infection and in homeostasis." (PMID 28659930, 2017). "The role of FDCs during homeostasis is less clear, but during infection FDCs support B cell movement and proper localization to GCs by producing CXCL13, as well as B-cell activating factor of the TNF family (BAFF) and a proliferation-inducing ligand." (PMID 28659930, 2017).
infection (continued). "Similar to BAFF, CXCL13 levels were elevated upon infection although the increase was progressive with the highest median of 275 pg/ml (range 125–511 pg/ml) being registered 90 DFOPV (the last visit analyzed)." (PMID 28943879, 2017). "Mechanistically, we found impaired CXCL13 chemokine induction early after infection in Il1r1−/− mice." (PMID 27579026, 2016). "CXCL13 levels were increased as soon as in the acute phase and throughout the course of infection in all viremic patients." (PMID 27203285, 2016). "These experiments demonstrate that appropriate innate IL-1α–IL-1R signaling is necessary for IAV clearance and at the same time instructs the formation of organized tertiary lymphoid tissues through induction of CXCL13 early after infection." (PMID 27579026, 2016). "Previous studies have shown that CXCL13 was induced in some microglia, macrophages, and endothelial cells in the CNS after infection or in infiltrating dendritic cells in EAE mice." (PMID 27401148, 2016). "In general, infection with both HS5cLP and HS5cLPΔggt induced a marked upregulation of CXCL13 in mice (p < 0.01)." (PMID 25889172, 2015). "Highest expression of CXCL13 was observed on days 1 [Mean [SD], 521 pg/ml] and 2 [523 pg/ml] post infection with levels decreasing progressively to day 7 when they were still above control values [P<0.005]." (PMID 24847941, 2014). "Mice were given 200 μg of polyclonal goat anti-CXCL13 and irrelevant polyclonal goat Ab the day prior to infection (d-1) and 2 days after infection (red arrows)." (PMID 23189125, 2012). "Mice treated with anti-CXCL13 Ab and Cxcr5−/− mice had increased chronic inflammatory or mononuclear cell scores when harvested 49 days after infection." (PMID 23189125, 2012). "Combined, our study suggests a key role of CXCL13 in B cell migration to sites of infection as shown here for the CSF of LNB patients." (PMID 20042073, 2009). "Most importantly, chemokine genes e.g., Cxcl9, Cxcl10, Cxcl11, Cxcl13, Ccl3, Ccl5 and Ccl12 that exert a chemotactic signal for the immune cell migration to the site of the injury were upregulated at 72 and 96 hr post infection." (PMID 18558011, 2008). "However, following the 4th IN infection, significantly increased CXCL13 levels were maintained for at least until 3-weeks post infection." (PMID 38576622, 2024). "Only after the fourth IN infection did the levels of CXCL13 become sustained in the plasma." (PMID 38576622, 2024). "Notably, in these mice, a significant increase in CXCL13 levels following 2nd infection also coincided with an increase in serum IgG." (PMID 38576622, 2024). "A significant transient increase in serum CXCL13 levels was noted at 3 days post 2nd, 3rd, and 4th IN infections (4.4- and 5.5-fold increase, respectively); however, at 3 weeks post 2nd and 3rd infection, CXCL13 levels had dropped to levels comparable to those in the naive sera." (PMID 38576622, 2024). "Indeed, using in situ hybridisation on independent tissue sections, we were able to confirm the presence of Ly6a+ Rarres2+ cells that expressed Cxcl13+ during infection." (PMID 37983289, 2023). "Interestingly, in one cohort study, the presence of antibodies against specific chemokines (CCL21, CXCL13 and CXCL16) was negatively associated with the development of LC at 1-year post-infection." (PMID 37445634, 2023). "The significant increase of CXCL13 in patients with lethal disease suggests this may be an emergency response to uncontrolled infection." (PMID 33472985, 2021). "This underlines that CSF CXCL13 can be a marker for infection and/or inflammation of the CNS and not a specific marker for LNB." (PMID 34132584, 2021). "Importantly, infection with CXCL13 short hairpin RNA (shRNA) mitigated EPC homing and angiogenesis, articular swelling, and cartilage erosion in ankle joints of mice with CIA." (PMID 34518512, 2021). "One of the main chemokines recruiting B-cells to the site of infection is also CXCL13." (PMID 34638953, 2021).